ALB (albumin)
Diseases named in the same sentence as ALB in open-access papers (continued):
Sharing a sentence is not in itself a finding about the gene and the disease.
Hypertension (continued). "Our study also explored the relationship between albumin (ALB) levels and stroke risk in individuals with hypertension, and similarly demonstrated a negative correlation between serum albumin levels and stroke risk." (PMID 40491586, 2025). "Foremost, there is a pressing need for longitudinal investigations to establish temporal relationships between serum albumin, uric acid levels, and hypertension progression, with particular emphasis on pre-RAAS activation events across diverse ethnic populations." (PMID 39897307, 2025). "Other significant factors included creatine kinase (CK) levels (OR = 1.001, P = 0.021), albumin (OR = 1.081, P = 0.012), and a history of hypertension (OR = 2.338, P = 0.014), whereas undergoing surgery was associated with a protective effect (OR = 0.313, P = 0.006)." (PMID 40303892, 2025). "Other variables included in the analysis, hypertension (p = 0.092), atrial fibrillation (p = 0.244), albumin (p = 0.065), LDL-C (p = 0.393), triglyceride (p = 0.148), total cholesterol (p = 0.539), hemoglobin (p = 0.799) and PIV (p = 0.873), were found to be non-significant." (PMID 40647616, 2025). "It facilitates the accounting of missing data on variables including the family PIR, level of education, alcohol consumption status, smoking habits, Scr, the ratio of urine albumin to creatinine, glycated hemoglobin, as well as histories of hypertension and cancer." (PMID 39319403, 2025). "Additionally, urinary albumin levels can be affected by conditions such as fever, infection, and hypertension." (PMID 40438382, 2025). "Moreover, the incremental improvement of the TyG-NLR model (ΔNagelkerke R2 = 0.02, LR χ2 = 50.8, P < 10-10) suggests that this index offers additional prognostic information beyond traditional factors such as hypertension, albumin, and uric acid." (PMID 41458543, 2025). "Chronic Ang II infusion induced evident hypertension and renal injury that is indicated by elevation of plasma creatinine, urinary albumin excretion, renal hypertrophy, podocyte injury, macrophage infiltration, and the expression of alpha smooth muscle actin and collagen deposition." (PMID 40165104, 2025). "Previous studies have confirmed that BBB dysfunction is a common occurrence in hypertension and the elderly, and the ratio of cerebrospinal fluid to serum albumin (CALB/SA) is one of the classic indicators for the detection of BBB, so we first analyzed the cerebrospinal fluid of SHRs." (PMID 40080509, 2025). "The analysis was conducted using three models, with Model 1 being unadjusted, Model 2 adjusted for age, gender, and race, and Model 3 adjusted for multivariate variables including age, gender, race, insulin use, hypertension, total cholesterol, blood urea nitrogen, serum albumin, and smoking status." (PMID 40920656, 2025). "Those with NGT or IGT were younger, and with lower levels of HbA1c, BMI, fasting blood glucose, creatinine, triglycerides, TyG index, TyG-WC, TyG-BMI, TyG-WHtR, CKD, hypertension rates, and with higher albumin, cholesterol levels and alcohol consumption rate (all P value < 0.05)." (PMID 40069759, 2025). "In our logistic regression analysis, we adjusted for the duration of T2DM, duration of hypertension, systolic blood pressure, waist circumference, DR, diabetic neuropathy, HbA1c, fasting glucose, urea, creatinine, cystatin C, and urine albumin–creatinine ratio." (PMID 40076459, 2025). "In 2012 (the print version of this article was published only in 2014), another study was presented on the connection between HSA and ACE: a large-scale screening of residents of the Japanese islands found that a low serum albumin level was a significant predictor of the development of hypertension." (PMID 39408590, 2024). "In addition, our study examined the utility of the lactate/albumin ratio in various subgroups inside the cohort of the COVID-19 critically ill patients, defined by age, sex, and history of hypertension and cardiovascular disease." (PMID 39685564, 2024).
Hypertension (continued). "Moreover, age, hypertension, diabetic retinopathy, eGFR, serum creatinine, cystatin C, calcium, hemoglobin, iPTH, albumin, LDL, IFTA, and arteriosclerosis were also significantly associated with adverse outcomes." (PMID 38571747, 2024). "Furthermore, we discovered significant differences (p < 0.05) in race, education level, marital status, family PIR, ALT, ALB, prevalence of hypertension, CVD and Mets, and insulin use among the OBS groups." (PMID 39145317, 2024). "However, SCI/MCI and AD patients with a follow-up visit differed in terms of systolic blood pressure, hypertension (%), CSF/serum albumin ratio, and CSF AD biomarkers (Aβ1–42, P-tau, and T-tau)." (PMID 38701139, 2024). "The initial variables that went into the model included age at admission, BMI, heart rate on admission, albumin value, initial absolute lymphocyte count on admission, vaccination group, race, elevated creatinine from baseline, hypertension, and home steroid use." (PMID 38515170, 2024). "A subgroup analysis revealed that the lactate/albumin ratio was significantly associated with mortality across different patient groups, including age and sex categories, and those with or without hypertension and coronary heart disease." (PMID 39685564, 2024). "Based on the results from the Cox proportional hazard model, we found that hypertension, renal insufficiency, and multi-vessel coronary disease were predictors of MACCE (HR: 1.25, 1.34, and 1.27, respectively), and albumin was associated with reduced risk of MACCE (HR: 0.98)." (PMID 38365597, 2024). "A five-year retrospective follow-up study in Japan found a positive association between serum albumin and serum potassium and a negative association with the development of hypertension." (PMID 38779492, 2024). "The results of univariate analysis showed that there were significant differences in age, history of hypertension, history of malignancy, baseline platelet values, TP, ALB, AST, DBIL, urea, and CCr between patients who developed thrombocytopenia and those who did not (p < 0.05)." (PMID 38449807, 2024). "Of the 32,464 participants aged ≥ 20 years, 30,232 were excluded because they had no history of cancer (n = 29,470), were less than 40 years of age (n = 217), had missing data for CRP (n = 407), albumin (n = 18), smoking status (n = 2), alcohol use (n = 119), and hypertension (n = 1)." (PMID 39358685, 2024). "Patients in the highest LnSII subgroup were more likely to have higher FPG, TC, triglycerides, LDL-C, and homocysteine; to have a higher proportion of hypertension prevalence and the use of oral hypoglycemic drugs; and to have a lower level of serum albumin (all P < 0.05)." (PMID 38409069, 2024). "Finally, the present study examined the diagnostic accuracy of BMI, IVS z score, serum urea, and serum albumin to predict the occurrence of hypertension in pediatric nephrotic syndrome patients." (PMID 39396026, 2024). "Among participants without hypertension, eGFR > 90 ml/min/1.73 m2 was inversely associated with 6-min walk distance, gait speed and knee flexion strength, while urinary albumin excretion > 30 mg/24 h was linked to significantly lower knee flexion strength." (PMID 38594601, 2024). "Hypertension significantly enhanced the effect of albumin-adjusted serum calcium on NAFLD." (PMID 38505748, 2024). "Differences were found in age, race, BMI, education, physical activity, energy, hemoglobin, uric acid, albumin, marital status, drinking, history of hypertension, CKD, depression, family heart attack, and CVD drug use between the survival and all-cause mortality groups." (PMID 40276135, 2024). "The associations of neutrophil-percentage-to-albumin ratio (NPAR) level with all-cause and cardiovascular disease (CVD)-cause mortality among patients with hypertension remain unclear." (PMID 39087072, 2024).
Hypertension (continued). "Fifth, some medications, such as Ibesartan, has some favorable impact in the course of renal failure among normotensive T2DM patients and reduced albumin excretion rate; however, in our study out of 162 hypertension medication user, only 82 individuals were on Angiotensin receptor blockers." (PMID 38300917, 2024). "In childhood TA, the risk factors could be a higher pain visual analogue score, increased neutrophil count, lower albumin levels, and arterial hypertension." (PMID 39087089, 2024). "However, the two groups exhibited significant differences in age, years of education, preoperative MMSE score, preoperative PSQI score, history of hypertension, preoperative hemoglobin levels, preoperative albumin levels, ASA grade, and BMI (p < .05)." (PMID 38747874, 2024). "In contrast, the hypermagnesemia group demonstrated a higher prevalence of the following: presence of hypertension, retinopathy, increased urine albumin/creatinine ratio, any stage of CKD, stages 4 and 5 CKD, elevated creatinine concentrations, reduced eGFR, and lower adjusted calcium concentration." (PMID 38791030, 2024). "The urinary albumin to creatinine ratio (UACR) is a common indicator of urinary albumin level and is associated with the incidence of cardiovascular events, particularly in individuals with DM, hypertension, or dyslipidemia." (PMID 37922304, 2024). "A positive relationship between albumin and potassium may inhibit the renin–angiotensin–aldosterone system, thus preventing hypertension development." (PMID 38779492, 2024). "However, the effects of Azilsartan on urinary albumin excretion in hypertension haven’t been reported before." (PMID 38462692, 2024). "In addition, there were significant differences in urea, creatinine, phosphorus, calcium, hemoglobin, blood albumin, eGFR, hypertension history, and medication between the CKD1–3a and CKD3b–5 groups." (PMID 39639681, 2024). "A 76-year-old man with a history of hypertension was admitted to nephrology on 25 November 2022 due to nephrotic syndrome, presenting with a serum albumin concentration of 15 g/L and an ACR of 10 g/g, complicated by acute renal failure with a serum creatinine level of 132 μmol/L." (PMID 38540991, 2024). "In this study, several factors were identified to be increasing the likelihood of acute mesenteric venous thrombosis (MVT), including smoking, high blood pressure, peritonitis, hemoglobin levels, albumin levels, intraperitoneal free fluid, decreased intestinal wall enhancement, and bowel distension." (PMID 38962741, 2024). "In addition, a study of 354 patients with essential hypertension showed an inverse correlation between worsening circadian blood pressure and the serum albumin concentration." (PMID 38779492, 2024). "Previous studies have demonstrated associations between DM, hypertension, heart failure, and gastrointestinal diseases (e.g., GERD, peptic ulcer disease, and ileus), underweight, age at onset, albumin, and hemoglobin with all-cause mortality in patients with schizophrenia." (PMID 38831863, 2023). "We found that age, gender, race, education level, marital status, income, drinking, physical activity, DM, hypertension, dyslipidemia, CVD, osteoporosis, arthritis, CKD, albumin, WBC, protein, and PUFA were associated with relative grip strength (all p < 0.05)." (PMID 38026307, 2023). "First, multivariate Cox regression analysis showed that DM, hypertension, heart failure, GERD, peptic ulcer disease, ileus, underweight, fasting glucose, triglycerides, albumin, and hemoglobin all contributed to the risk of all-cause mortality in the enrolled patients with chronic schizophrenia." (PMID 38831863, 2023). "In addition, age, triglyceride level, and the prevalence of hypertension and insulin use differed significantly according to the quartiles of urinary albumin excretion." (PMID 37916147, 2023).
Hypertension (continued). "In addition to age and sex, race/ethnicity, eGFR, history of cardiovascular disease and hypertension, smoking history, BMI, and urinary albumin are used for calculation." (PMID 36973534, 2023). "The findings of the univariate analysis indicated that hypertension (p = 0.026), a lower albumin level (p = 0.002), a higher AFP level (p = 0.035), a lower creatinine level (p = 0.018), and a higher baseline eGFR (p = 0.005) were associated with a large eGFR decline." (PMID 36766578, 2023). "For example, the WHipple-ABACUS score for 30-day mortality following PD takes into account hypertension, history of cardiac operations, age >62 years, bleeding disorder, albumin <3.5 g/dL, disseminated cancer, use of steroids, and preoperative systemic inflammatory response syndrome (SIRS)." (PMID 37881394, 2023). "While inflammation level was correlated with depression (r = 0.133), age (r = 0.256), etiology of ESRD (r = 0.125), combined hypertension (r = 0.143), phosphorus (r = 0.134), iPTH (r = 0.113) and triglyceride (r = 0.156), but negatively correlated with albumin (r = -0.138) (all p < 0.05)." (PMID 37587401, 2023). "Six predictors were determined using LASSO regression, including baseline albumin-to-creatinine ratio, glycated hemoglobin, hypertension, retinol-binding protein-to-creatinine ratio, quartiles of fasting C-peptide, and quartiles of fasting C-peptide to 2h postprandial C-peptide ratio." (PMID 37576977, 2023). "The glycation of blood proteins, such as hemoglobin, albumin, LDL, and HDL, is linked to the exacerbation of hypertension via oxidative stress and an inflammatory process of advanced glycation end products to form atherosclerotic plaque and cause aortic stiffness." (PMID 36982259, 2023). "Funnel plot analysis revealed asymmetry with respect to hypertension, incidence of female sex, albumin level, and renal insufficiency, suggesting a potential publication bias or selective reporting of studies with significant or positive results for these variables." (PMID 37848510, 2023). "Model 1 was crude, in model 2 we adjusted for sex and BMI, and in model 3 we adjusted for sex, BMI, serum albumin, concurrent history of hypertension and DM, liver cirrhosis, congestive heart failure, cerebrovascular accident, and history of hospitalization (within 6 months)." (PMID 37784041, 2023). "In addition, age, BMI, comorbidity (hypertension or PH), PaCO2, and albumin were also significantly correlated with COPD prognosis (all P < 0.05)." (PMID 37183240, 2023). "Adjusted variables: age, sex, education, marital status, poverty-income ratio, BMI, hypertension, smoking, regular exercise, albumin level, blood urea nitrogen level, chloride level, dietary carbohydrate intake, dietary total sugar intake, and dietary cholesterol intake, and high blood pressure." (PMID 38027115, 2023). "This study successfully developed a predictive model for cerebral small vessel disease (CSVD) that incorporates nine clinical predictive factors including gender, age, history of stroke, carotid atherosclerosis, hypertension, creatinine, Lipoprotein(a), Albumin/Globulin Ratio, and homocysteine." (PMID 38259650, 2023). "In the multivariate logistic regression analysis, the higher renal scores, presence of DM, and younger age were independently predicted for renal disease progression after adjusting for confounding variables, such as the presence of hypertension, serum hemoglobin and albumin levels, and UPCR." (PMID 36766619, 2023). "The results of univariate analysis showed that patients with higher BMI (P = 0.004), hypertension history (P = 0.024), lower serum prealbumin level (P = 0.032), lower serum albumin level (P = 0.001), a thicker pancreas (P < 0.001) and a soft pancreas (P = 0.001) were more likely to develop CR-POPF." (PMID 36631791, 2023).
Hypertension (continued). "As human albumin is the most copious antioxidant in the whole blood, the insufficiency of SA will initialize oxidative stress and inflammation, which play a key role in the pathogenesis of hypertension and multiple CVDs." (PMID 36937935, 2023). "After adjusting for age, sex, hypertension, proteinuria, albumin, eGFR, PLA2R antibody, and treatment, thyroid dysfunction remained an independent risk factor for IMN relapse (HR = 1.726, P < 0.001) and composite endpoint event (HR = 1.576, P = 0.043), but not for CR (HR = 0.941, P = 0.486)." (PMID 37008916, 2023). "Model II which was further adjusted for age, gender, department, serum sodium, serum albumin, serum-magnesium tertiles, hypertension, heart failure, chronic renal failure, and pneumonia also revealed that GPR was independently associated with 30-day mortality (OR 2.01, 95% CI 1.12–3.61)." (PMID 35581319, 2022). "This study found that the elderly with old age, female, married but not living with a spouse, low plasma albumin, high urea acid and hypertension have a high risk of CKD, which is consistent with the results of several studies." (PMID 36339144, 2022). "Also, in women with hypertension, the presence of protein-binding hormones in the urine and a decrease in serum albumin due to proteinuria can lead to a decrease in TT3 levels." (PMID 36163002, 2022). "Univariate logistic regression showed that age, sex, smoking, drinking, SBP, past history of hypertension, past history of DM, past history of dyslipidemia, serum albumin, fasting glucose, total cholesterol, triglyceride, and CKD were significantly associated with incident cataracts." (PMID 36568781, 2022). "Factors showing significant difference in univariate analysis, including age, gender, BMI, type of surgery, PSQI score, preoperative albumin, hypertension, atherosclerosis, digestive diseases, number of comorbidities and ASA grade, were included in the multivariate logistic analysis model." (PMID 35855669, 2022). "Compared with the non-IgAN group patients in the training cohort, the IgAN group patients were significantly younger on average, had a higher incidence of hematuria and hypertension, and had higher levels of serum albumin, urea nitrogen, creatinine, uric acid, IgA, IgG, and IgA/C3 ratios (P < 0.01)." (PMID 35585099, 2022). "The LASSO analysis screened the following as risk factors: blood loss; ejection fraction (EF); forced expiratory volume in 1 s; preoperative albumin (Alb); postoperative hemoglobin (Hb); preoperative Hb; hypertension; time to surgery; age; and left atrial (LA) diameter." (PMID 36684273, 2022). "A BI ≤ 24 h was not a significant risk factor for infectious complications at each follow-up timepoint after adjustment for center, sex, age, temporary HD usage, dialysis mode during the BI period, combined hypertension, hemoglobin, albumin, HDL, LDL and BG (p > 0.05)." (PMID 35272577, 2022). "Predictors of improved OS were lenvatinib dose reduction (HR 0.38, 95% CI 0.23–0.63, p < 0.01) or withholding therapy (HR 0.44, 95% CI 0.24–0.82, p < 0.01), a higher baseline albumin (HR 0.89, 95% CI 0.85–0.93, p < 0.01) and the development of hypertension (HR 0.56, 95% CI 0.34–0.94, p = 0.02)." (PMID 36006547, 2022). "Third, the procedure to enrich the PREVEND cohort with participants with an urinary albumin concentration at least 10 mg/l may have increased the number of participants with hypertension at the baseline of the current study." (PMID 34371517, 2022). "After adjusting for age, sex, BMI, hypertension, DM, hemoglobin, albumin, creatinine, LDL, HbA1c, hsCRP, and TMAO, increased TML levels remained associated with significantly increased odds for HF (tertile 3 (T3) vs. tertile 1, OR: 1.93, 95% CI: 1.19–3.13, P = 0.007)." (PMID 36247428, 2022). "Moreover, in the CKD group, BMI, SBP, DBP, uric acid and the prevalence of hypertension and DM were significantly high, whereas serum albumin level was low." (PMID 36086712, 2022).